CCL22 (C-C motif chemokine ligand 22)
Diseases named in the same sentence as CCL22 in open-access papers (continued):
Sharing a sentence is not in itself a finding about the gene and the disease.
tumor (continued). "M2 macrophage-derived cytokines promote an immunosuppressive tumor microenvironment, including CCL22, IL-10, and TGF-β1, that were significantly correlated with LILRB1 expression GC patients." (PMID 34485116, 2021). "Another important actor in the FL milieu is the chemokine CCL22, secreted by FL tumor cells as a result of the CD40L–CD40 axis activated by TFH." (PMID 33562694, 2021). "For Ccl5, Ccl22, Ccl27a, Ccl28, and Cxcl12, chemokines known to exert pro-tumor effects, substantially higher levels were noted in the liver." (PMID 33985562, 2021). "CCL22 serum levels and CCL22 expression in tumor beds were shown to be higher in GC patients than in healthy controls." (PMID 34830815, 2021). "Together, these results indicate that L1CAM recruits Tregs to tumor sites, thereby promoting tumor progression by regulating CCL22 secretion in vitro and in vivo." (PMID 33710805, 2021). "A nomogram integrating data on CCL22 expression and other characteristics, including age, gender, tumor grade, T stage, and N stage, was constructed, wherein a worse prognosis was represented by a high score on the nomogram." (PMID 34391381, 2021). "In ovarian cancer, tumor cells and TAMs produce the chemokine CCL22, which mediates the recruitment of Treg cells to the tumor, suppressing anti-tumor immunity." (PMID 34283042, 2021). "CCL17 and CCL22 induced by CD40 stimulation on B-cell leukemia cells have been shown to attract CCR4+ tumor-specific T cells." (PMID 33666760, 2021). "As such, elevated expression of CCL22 is correlated with lower spontaneous and therapy-induced T-cell antitumor immunity, leading to tumor growth and poor patient outcomes." (PMID 34575965, 2021). "Tregs are selectively trended into tumor tissues by tumor cells in a CCL22- and CCL28-dependent manner; subsequent Treg-induced secretion of VEGF-A by cancer cells promotes endothelial cell proliferation." (PMID 34063848, 2021). "Factors secreted from the local tumor stroma can induce the expression of PD-L1 on tumor-activated monocytes, while M2-derived C-C motif chemokine ligand 22 (CCL22) can enhance Treg cells trafficking into the intratumoral compartment." (PMID 35310881, 2020). "Treg cells express CCR4 and are recruited into the tumor micro environment in response to CCL22, which is produced mainly by macrophages and tumor cells." (PMID 33262763, 2020). "CCL17 and CCL22 are responsible for CCR4-dependent recruitment of Treg into the tumor niche, which enhances cancer immune evasion." (PMID 33182504, 2020). "CCL22 correlates with a systemic inflammation response index that predicts survival of patients with PDAC, and APP has been linked to tumor growth in experimental cancers, including PDAC." (PMID 33334063, 2020). "High levels of CXCR4, a receptor correlated with tumor malignancy, and CCL22, a member of the chemokine family, are related to migration, invasion, and metastasis in various tumors, leading to a poor prognosis and malignant progression." (PMID 32102251, 2020). "CCL22 has an effect on repressing immune responses to tumor cells through its ability of recruiting Treg and Th2-cells, thereby enhancing tumor development." (PMID 32977823, 2020). "CCL22, secreted by tumor cells and TAMs, activates trafficking of Treg cells within the tumor as well as promotes tumor migration and invasion." (PMID 32824865, 2020). "CCL22 is produced by macrophages, dendritic cells and tumor cells and is a chemoattractant for several cell types including regulatory T cells and T helper type 2 cells, as evidenced by their expression of the CCL22 receptor, CCR4." (PMID 33202734, 2020). "Characterized by their hallmark cytokines, IL-10 and TGF-β, which can effectively suppress tumor-specific T cell activation, Tregs are attracted to the local tumor environment by soluble mediators, such as CCL22 or CCL2 produced by glioblastoma cells." (PMID 32117316, 2020).
tumor (continued). "MiR‐23a inhibitor promoted xenografted tumor growth accompanying with upregulation of CCL22, whereas p65 inhibition exerted opposite effects." (PMID 31769216, 2020). "While IL-1β and IL-6 have been linked to the generation of MDSC inside tumor tissues, CX3CL1 and CCL22 have been found to induce the recruitment of MDSCs into the tumor microenvironment in tumor-bearing hosts." (PMID 32632113, 2020). "Blockage of p65 was sufficient to recover miR‐23a expression in tumor cells, which then repressed CCL22 expression and Tregs recruitment into tumor tissues." (PMID 31769216, 2020). "TGF-β released by tumor cells can upregulate the expression of IDO in pDC and the secretion of cytokine CCL22, which recruits Tregs into the tumor microenvironment." (PMID 33584699, 2020). "As expected, both CCL22 and Foxp3 (marker of Tregs) mRNA levels were increased in tumor samples when compared with in adjacent normal tissues." (PMID 31769216, 2020). "Our ability to rescue, in part, Treg recruitment and tumor growth in Siah2−/− mice subjected to treatment with neutralizing antibodies to Ccl17 and Ccl22 further illustrates the independent pathways by which Siah2 controls tumor growth." (PMID 31911617, 2020). "Of note, CCL22, a key gene mediates Tregs recruitment and tumor immune evasion, was found in the candidate list." (PMID 31769216, 2020). "As a prognostic factor in BrCa, tumor derived CCL22 has also been shown to activate and recruit CCR4 expressing Tregs56,57." (PMID 30850664, 2019). "In ovarian cancer, for instance, CCL22 was found to induce regulatory T (T-reg) cells into tumor mass and inhibit T cell immunity." (PMID 31842422, 2019). "In BCCs, the chemokines, CCL-17, CCL-18, and CCL-22 that recruit Tregs are overexpressed in the tumor islands and peritumoral skin." (PMID 31134198, 2019). "TAMs exert a pro-tumor effect, inhibiting antitumor activities by secreting chemokines such as CCL17, CCL18 and CCL22, which attract Tregs cells to tumor sites, compromising the immune responses of CD8 + cytotoxic T cells." (PMID 31600917, 2019). "The chemokine CCL22 recruits regulatory T (T-reg) cells into tumor tissues and is expressed in many human tumors." (PMID 31842422, 2019). "Overexpression of CXCL2 or CCL22, or depletion of CD8a, impaired ttIL-12’s efficacy in suppressing tumor growth and metastasis, which validated the novel mechanism of ttIL-12 in converting a short OS immune profile to a long OS immune profile." (PMID 31208461, 2019). "Another important mechanism contributing to tumor expansion is the recruitment of regulatory T cells (Tregs) by M2-derived C-C motif chemokine ligand 22 (CCL22)." (PMID 30328949, 2018). "Both IP-10 and CCL22 are involved in lymphocyte chemotaxis and recruiting regulatory T cells to the tumor microenvironment." (PMID 29668679, 2018). "One of the most extensively described mechanisms of Treg attraction to tumor sites is intratumoral expression of the chemokine CCL22." (PMID 30572845, 2018). "CXCL12, CCL17 and CCL22 play a role in the recruitment of T-regs to tumour sites and thereby inhibition of anti-tumour response." (PMID 28987144, 2017). "Tumor cells and microenvironmental macrophages produce CCL22, thereby recruiting Treg cells and suppressing tumor-specific T cell immunity." (PMID 29099057, 2017). "In ovarian cancer CCR4+Tregs migrate towards CCL22 produced by tumor cells or by the tumor microenvironment, thereby creating favorable conditions for tumor growth." (PMID 28415693, 2017). "CCL17 and CCL22 expression was upregulated in several organs including lung, liver and brain of the tumor-bearing nude mice harboring these highly malignant tumors." (PMID 28415693, 2017). "CCL22 is thought to be involved in diverse pathologies, ranging from allergic reactions and autoimmunity to tumor growth." (PMID 29099057, 2017). "We also examined the effects on tumor-promoting markers related to Treg cells, including CCL22, CXCL12 and FoxP3." (PMID 26956047, 2016).
tumor (continued). "The secretion of CCL22 by macrophages has a chemotaxis effect on Treg cells trafficking, which are suppressive and able to block tumor-specific immunity." (PMID 27775051, 2016). "miR-34 can also function in a feedback loop to tumor growth factor-beta (TGFβ), regulating the chemokine CCL22 and tumor immune escape via recruitment of Tregs." (PMID 26577528, 2016). "Th2 related chemokines CCL5 and CCL22 preferentially recruit T cells that lack the capacity to eliminate tumor cells by direct lysis, i.e., regulatory T cells and Th2 cells; the latter bias immune responses away from Th1." (PMID 26943036, 2016). "A recent study showed that M2 macrophages-derived CCL22 directly promote tumor migration capacities and correlate with venous infiltration." (PMID 27775051, 2016). "The selective recruitment of Treg by tumor-derived endothelial cells is in part response by Treg to chemokines such as CCL-22, which is expressed by TAM." (PMID 27191744, 2016). "In the following study, we have carefully analyzed the concentration of CCL22 in the PF and plasma of women with different stages, grades, and histological types of tumor." (PMID 25647263, 2015). "In the present study we investigated the effects of tumor-induced chemotaxis of Treg cells in vitro and the potential role of CCL22 or CCL17 in this process, and demonstrated that SSCC and NIP both significantly increased the chemotaxis of Treg cells." (PMID 26020249, 2015). "Apparently increased CCL22 attracted CCR4-expressing Treg cells to tumor microenvironment in SSCC, compared to NIP." (PMID 26020249, 2015). "The authors also detected large amounts of CCL22 in tumor ascites, but only in 18 patients with EOC." (PMID 25647263, 2015). "The mechanism of Treg cells migration was related to the presence of the CCL22 chemokine which is released by the tumor cells and their surrounding macrophages." (PMID 26077607, 2015). "Even more, CCL17/TARC and CCL22/MDC produced by both tumor and infiltrating cells in different types of cancer are able to recruit CCR4+ regulatory T and polarized Th2 cells that inhibit anti-tumor responses contributing to tumor survival." (PMID 26062132, 2015). "CCL22 on tumors recruits CCR4+ Treg cells to the site and has been associated with tumor progression through their suppression of effector T cells that target tumor antigens." (PMID 26834735, 2015). "Tumor cells and macrophages in the tumor microenvironment produce CCL22, which mediates trafficking of Tregs to the tumor and poorer prognosis in EOC." (PMID 25888637, 2015). "Circulating Treg cells were recruited to tumor tissue via CCR4/CCL22 signalling, whereas tumor-synthesised TGF-β contributed to induction of peripheral Treg cells." (PMID 26020249, 2015). "CCL2, CCL22, TGF-β and IL-10 augment the differentiation of M2-like tumor-associated macrophages (TAMs) and recruitment of immunosuppressors including TAMs, MDSCs and Tregs." (PMID 26683520, 2015). "A number of tumor-bound chemokines including CCL22 have been shown to recruit Tregs to modulate immune responses in cancer." (PMID 25743773, 2015). "CCR4/CCL22 even induces Tregs to selectively infiltrate into a particular site in the tumor, such as the area of lymphoid aggregates where Tregs are activated and proliferate in response to tumor-associated antigens presented by DCs." (PMID 25110692, 2014). "As a mechanism of Treg recruitment to tumors, it has been proposed that the tumor cells and tumor infiltrating macrophages produce the chemokine CCL22, which attracts and recruits CD25+ CD4+ Tregs expressing CCR4." (PMID 25080123, 2014). "Our findings demonstrated that the expressions of both tumor-secreted CCL22 and TGF-β1 were positively correlated with the intratumoral Tregs at the immunohistochemistry level." (PMID 24124553, 2013).
tumor (continued). "The chemokine receptors, CCR10 and CCR4, known to respond to chemo-attractants CCL27, MCP-1, and CCL22, have been shown to be critical in inducing mobilization and homing of myeloid cells and leukocytes to the tumor site." (PMID 23372791, 2013). "It is also apparent that the relationship between Treg cells and NK cells is reciprocal, as NK-dependent increases in CCL22 secretion selectively recruits Treg cells to the tumor microenvironment." (PMID 23378947, 2013). "CCL22 is a chemokine produced by B cells, myeloid dendritic cells, macrophages and epithelial cells in the tumor microenvironment." (PMID 24312199, 2013). "Several studies have demonstrated that CCL22 can selectively recruit Tregs into the tumor microenvironment, resulting in the accumulation of Tregs." (PMID 24124553, 2013). "Researchers have recently identified that the interaction between natural killer (NK) cells and tumor cells can drive tumor cells to produce CCL22." (PMID 24124553, 2013). "TC-1 tumours contain infiltrates of immune suppressive Tregs, recruited following secretion of the CCL22 chemokine by tumour cells." (PMID 23799135, 2013). "In support of the first possibility, studies performed by Zou and colleagues demonstrated specific recruitment of pre-existing human Treg cells into tumors in a manner that was dependent on tumor-mediated CCL22 production and gradient." (PMID 23874336, 2013). "While the secretion of CCL22 and CCL17 has been implicated in Treg recruitment to the tumor microenvironment in several studies, the role of these chemokines in the recruitment of Tregs to inflammatory sites during Mtb infection has yet to be addressed." (PMID 23785280, 2013). "The results showed that CCL22+Foxp3high+ in the tumor bed was predicted a worse survival, which further confirmed that CCL22 was in interaction with Tregs." (PMID 24124553, 2013). "Stimulation of BM myeloid cells by crosslinking CD79a induced the secretion of several cytokines associated with tumor and metastasis promotion, in particular IL-6, RANTES, TNFR-II, CXCL16 and CCL22." (PMID 24146823, 2013). "Several studies indicate that the tumor-expressed chemokines CCL22 and CCL17, which are ligands for CCR4, play a role in the recruitment and enrichment of Tregs." (PMID 23874342, 2013). "Chemokines play a role in migratory events, as tumor cells and microenvironmental macrophages produce the chemokine CCL22, which mediates trafficking of Treg cells to the tumor." (PMID 23378947, 2013). "Similar to Foxp3 expression in BC, upregulation of CCL22 expression in tumor cells was significantly more common in carcinomas with unfavorable histological features, such as high tumor grade, ER-negativity, PR-negativity and HER2-overexpression." (PMID 24124553, 2013). "Although exact mechanisms are not fully explored, it has been shown that CCR4+ (receptor for CCL22) Tregs migrate toward tumour microenvironments expressing CCL22." (PMID 22778767, 2012). "Previous evidence suggested that chemokine family members, such as CCL17 and CCL22, direct the movement of Tregs in tumor mass." (PMID 21655250, 2011). "Blocking CCL22 with siRNA during the differentiation and maturation of DC can block Treg recruitment, thus this is a good target for inhibition of tumor-induced immune suppression." (PMID 22013484, 2011). "Blood Treg have been shown to express high CCR4 and to selectively migrate in response to the CCR4 ligand CCL22 produced by tumor cells but also by tumor infiltrating DCs." (PMID 22110524, 2011). "Moreover, a significant correlation was established between the frequency of CCL17(+) or CCL22(+) cells and Foxp3(+) Tregs within tumor-infiltrating lymphocytes." (PMID 40134607, 2025). "In addition, CAF-derived IL-1β initiates transcriptional upregulation of the chemokine CCL22 in tumor cells through NF-κB activation, thereby facilitating regulatory T cell (Treg) recruitment and reinforcing local immune suppression." (PMID 41583435, 2025).
tumor (continued). "Additionally, CCL22-based peptide vaccines have been investigated for their ability to induce anti-cancer immunity by modulating the tumor microenvironment, highlighting the role of this chemokine in immune regulation." (PMID 40181376, 2025). "Moreover, chemokines such as C-C motif chemokine ligand 22 (CCL22) recruit immunosuppressive Tregs to the tumor site via C-C chemokine receptor type 4 (CCR4)." (PMID 40672956, 2025). "However, tumor‐infiltrating regulatory T cells (Tregs), recruited via chemokines such as CCL22, suppress the anti‐tumor immune response, creating an immunosuppressive microenvironment." (PMID 40922069, 2025). "Furthermore, tumor cells overexpress the chemokine CCL22 by inducing eosinophils, and CCL22 can be used to recruit Tregs, helping tumors establish a pre-metastatic niche, thereby promoting tumor metastasis." (PMID 40131539, 2025). "Additionally, TAMs induced immune checkpoint inhibition of T cells by upregulating PD-L1 expression and recruited Tregs via CCL22 to further suppress anti-tumor immune responses." (PMID 40936936, 2025). "CCL17 and CCL22 also shape anti-tumour immunity, generally to the host’s detriment." (PMID 41291326, 2025). "CCL22 can recruit a large number of Tregs to exert an inhibitory effect, and Tregs further recruit relevant immune cells with immunosuppressive functions, forming a vicious cycle and blocking the anti-tumour effect of the immune system." (PMID 38475858, 2024). "In addition to the CXCL12-CXCR4 axis, chemokines CCL12 and CCL22 enhance tumor cell formation in the bone marrow microenvironment and are involved in tumor transformation, growth, and metastasis." (PMID 38770000, 2024). "Its ligands, CCL17 and CCL22, are mainly released by tumor cells and TAMs." (PMID 39596815, 2024). "Similarly, macrophage-derived CCL22 can either suppress tumor immunity by increasing Treg cell tumor infiltration or promote tumor immunity by recruiting helper T cells." (PMID 39114657, 2024). "Specifically, C–C Motif Chemokine 22 (CCL22), a crucial immunosuppressive chemokine involved in the recruitment of regulatory T cells to the tumor microenvironment, was found to be decreased in tumor tissues of the combination therapy group." (PMID 39431325, 2024). "CCL22 is a chemokine involved in the pathophysiology of infectious and neoplastic diseases." (PMID 38473935, 2024). "Some reports describe that the tumor immune escape can be driven by other immunosuppressive cytokine loops, including CCL22, CCL17, and CCL18 that are also secreted by macrophage for recruiting Treg cells and modulate the immune response during the tumorigenic process." (PMID 39061137, 2024). "Interestingly, the authors identified that the CCL22 released from PBMCs was due to the IL-1α released from tumor cells." (PMID 38339310, 2024). "Treg cells express CCR4 and are recruited to the tumor microenvironment by CCL22 induction." (PMID 39136031, 2024). "However, a closer look at the mRNA and intracellular protein levels in tumor cells revealed also an induction of CCL22 in tumor cells." (PMID 39232378, 2024). "While the exact regulation and function of CCL22 in tumor cells needs to be further elucidated, our data suggest that CCL22 levels in stroma and myometrium might be an important parameter for the intratumoral accumulation of immunosuppressive Treg." (PMID 39232378, 2024). "Tumour cell-derived IL-1α is a major inducer of Tregs that attracts the chemokine CCL22, and therapeutic blockade of the IL-1 pathway may also be an effective approach to limiting tumour-induced immunosuppression." (PMID 38475858, 2024). "It is tempting to speculate that tumor cells might be prevented from secreting CCL22 under certain circumstances, although intracellular expression is increased." (PMID 39232378, 2024). "CCL22 increases regulatory T cell (Treg) infiltration in tumors and promotes tumor growth." (PMID 39027151, 2024).